CD36 (CD36 molecule (CD36 blood group))
Diseases named in the same sentence as CD36 in open-access papers (continued):
Sharing a sentence is not in itself a finding about the gene and the disease.
atherosclerosis (continued). "Loss of Ash2l abundance at the promoter of PPARγ inhibited CD36 transcription, which significantly weakened the proximity ligation signals between TLR4 and CD36, thus reducing NF-κB signal activation and contributing to the protection against endothelial injury and atherosclerosis." (PMID 38280036, 2024). "Additionally, CD36 has been found to exhibit crosstalk with PPARδ in macrophages, impacting foam cell formation and inflammation in atherosclerosis and in induced inflammation from M. leprae infection models." (PMID 38989454, 2024). "In vivo and ex vivo experiments were conducted to figure out whether NOB inhibits lipid uptake and the progression of atherosclerosis by modulating the PPARG/CD36 signaling pathway." (PMID 38468335, 2024). "CD36, a widely expressed scavenger receptor on various immune and non-immune cells, mediates numerous biological processes including inflammation, angiogenesis, atherosclerosis, and innate immunity." (PMID 38926392, 2024). "CD36 is a well-established contributor to the development of atherosclerosis yet its role in mediating early stages of disease processes remains unknown." (PMID 38586877, 2024). "Agarwood also has therapeutic effects in treating cardiovascular diseases, where 2-(2-phenylethyl) chromone derivatives can mitigate atherosclerosis by reducing endoplasmic reticulum stress-mediated macrophage CD36 expression and inhibiting foam cell formation." (PMID 39323637, 2024). "These lipids may chronically bind and activate CD36 in both adipocytes and macrophages, leading to adipose tissue dysfunction and abnormal lipid metabolism and deposition, as observed in atherosclerosis." (PMID 39156133, 2024). "Nobiletin alleviates atherosclerosis by inhibiting lipid uptake via the PPARG/CD36 pathway." (PMID 38468335, 2024). "Since CD36 null humans are common in some areas and they appear to have a normal life expectancy and no obvious increased risk for specific diseases, our results highlight the possibility of designing specific CD36 inhibitors against chronic inflammatory metabolic diseases, such as atherosclerosis." (PMID 39156133, 2024). "Therefore, the activation of the TDP43/PPAR-γ/CD36 axis is a new mechanistic model that explains increased LDL/oxLDL uptake by macrophages during atherosclerosis." (PMID 39528464, 2024). "In addition to its role in lipid metabolism and inflammation, PPARγ is also closely related to CD36, a core gene among the marker genes we are currently investigating, further underscoring its significance in atherosclerosis." (PMID 39660117, 2024). "However, it is important to note that the CD36-PPARγ pathway also plays a role in the early stages of atherosclerosis development." (PMID 39660117, 2024). "Furthermore, 7-ketocholesterol plays a role in promoting thrombosis, atherosclerosis, and endothelial dysfunction through CD36 pathways." (PMID 39464269, 2024). "CD36 may also be involved in diabetes, glucose intolerance, and atherosclerosis, so that LOLA may have additional beneficial effects on different manifestations of metabolic dysregulation including the MetS." (PMID 38675168, 2024). "Thus, Lab4b CM attenuated the expression of two key scavenger receptors, SRA and CD36, which have been shown to promote atherosclerosis in vitro and in vivo." (PMID 36835055, 2023). "CD36 has the important role in atherosclerosis pathophysiology." (PMID 37254185, 2023). "Lastly, given the fact that CD36 can be a therapeutic target of interest in the treatment of the common co-morbidities of cancer patients, such as atherosclerosis and diabetes, anti-CD36 therapy also has the potential to concurrently correct these systemic metabolic dysfunctions." (PMID 37371076, 2023).
atherosclerosis (continued). "MMP9, MMP12, FABP4, and CD36 might be the potential therapeutic targets in treating atherosclerosis and NSCLC." (PMID 37978381, 2023). "TMAO induced atherosclerosis through the CD36-dependent MAPK/JNK pathway." (PMID 37337893, 2023). "CD36 plays an important role in the development of atherosclerosis." (PMID 40625574, 2023). "Their activation is associated with a slowed progression of atherosclerosis through an inhibition of NF-κB activity, resulting in a decreased production of pro-inflammatory cytokines, as well as inhibited LDL uptake via a lowered expression of CD36." (PMID 36982492, 2023). "We have identified seven genes (CHI3L1, CD36, LEPR, RETN, IL-18, RBP-4, and RARRES2) that may be associated with IR and atherosclerosis as having possible evidence based on the disease pathogenesis of ED and inflammation." (PMID 36984867, 2023). "We hypothesized that atorvastatin could inhibit the expression of MMP9, MMP12, FABP4, and CD36 in patients with atherosclerosis and NSCLC." (PMID 37978381, 2023). "The purpose of this study is to investigate whether SFN treatment could influence macrophage foam cell formation and atherosclerosis and explore the potential mechanistic contribution of CD36, ABCA1/G1 expression and the involvement of PPARγ and Nrf2." (PMID 37432260, 2023). "Similar, another recent animal study suggested that iron overload could diminish atherosclerosis in apolipoprotein E knockout mice by interfering with hepatic CD36 and fatty acid binding proteins-mediated fatty acid uptake and transport." (PMID 37275636, 2023). "CD36 regulates a variety of physiological and pathological processes, including FA transport and lipid metabolism, angiogenesis, adhesion, inflammation, cardiomyopathy, diabetes and atherosclerosis." (PMID 37248406, 2023). "In this study, we found that CD36 was highly expressed in atherosclerosis." (PMID 37978381, 2023). "Additionally, a soluble form of CD36 (sCD36) in plasma has been demonstrated to represent a potential surrogate marker of atherosclerosis." (PMID 37432260, 2023). "Moreover, a recent study discovered that KCa3.1 modifies the development of atherosclerosis via the STAT3/CD36 signaling axis." (PMID 37588590, 2023). "Links CD36 expression to the onset of atherosclerosis in peripheral blood mononuclear cells." (PMID 38046702, 2023). "CD36 is correlated with the occurrence and development of atherosclerosis." (PMID 37978381, 2023). "Earlier reports suggested that the CD36 (cluster of differentiation 36), a transmembrane glycoprotein receptor, plays an important role in athero-thrombotic activity and promotes the pathological conditions such as atherosclerosis and thrombosis." (PMID 36769293, 2023). "The lack of associations does not resolve doubts about the relationship between CD36 gene polymorphism and parameters of atherosclerosis progress manifested in subsequent cardiovascular episodes." (PMID 37239003, 2023). "In an animal model of atherosclerosis, TMAO promoted the formation of foam cells and the progression of atherosclerosis, enhancing macrophage recruitment, and the expression of pro-inflammatory cytokines and adhesion molecules via the CD36/MAPK/JNK signaling pathway." (PMID 36834796, 2023). "Macrophage infiltration and low‐grade inflammation in abdominal obesity may lead to dyslipidemia, lipoprotein peroxidation, and liver steatosis, and these factors promote the development of atherosclerosis and induce CD36 in the vascular wall." (PMID 40625574, 2023). "CD36 plays a major role in regulating atherosclerosis via a variety of pathways." (PMID 37409245, 2023). "The inhibition of foam cell formation by macrophages was based on the suppression of cyclin-dependent kinase 5 (Cdk5)/CD36 pathway, a pathway that has been correlated with LPS-induced inflammation and advanced glycation end products (AGEs)-derived atherosclerosis." (PMID 36834796, 2023).
atherosclerosis (continued). "CD36 is responsible for the uptake of cholesterol by macrophages and supports their transformation into lipid-loaded foam cells which are involved in the formation of atherosclerosis-like lesions in the microvasculature." (PMID 37658922, 2023). "The CD36 is the predominant scavenger receptor for oxLDL, and the binding between CD36 and oxLDL triggers TLRs signaling pathway to promote pro-inflammatory responses to mediate the progression of foam cell formation and atherosclerosis." (PMID 37588590, 2023). "Higher production of IL-1β might be involved, at least in part, in the acceleration of atherosclerosis in Apoe-/-Card9-/- mice and might be due to increased CD36 expression." (PMID 37528097, 2023). "CD36 is one of the main scavenger receptors, which could promote macrophage foam cell formation in atherosclerosis." (PMID 37047475, 2023). "Collectively, CD36 dysfunction has been shown to contribute to the pathologies of atherosclerosis." (PMID 36769293, 2023). "Among them, CD36, CDC42, JAK2, and STAT3 proteins were closely associated with atherosclerosis and foam cells, and their protein expressions were opposite to those of the ox-LDL group and converged with those of the control group after the sinapine base intervention." (PMID 36903257, 2023). "The sEV FA uptake pathway might contribute to some of CD36 actions in metabolism, atherosclerosis, and immunity as the findings could apply to CD36 ligands other than FAs." (PMID 37419919, 2023). "CD36, a glycoprotein located on the surface of platelets, macrophages, monocytes, adipocytes, and endothelial cells, is considered a significant player in the development of atherosclerosis." (PMID 36506940, 2022). "CD36 was also differentially expressed and downregulated on the lipid and atherosclerosis pathway." (PMID 36506940, 2022). "DCHP exposure increased CD36 expression and foam cell formation in macrophages of PXRF/FLDLR−/− mice, but deficiency of myeloid PXR inhibited DCHP-elicited macrophage dysfunction and atherosclerosis in PXRΔMyeLDLR−/− mice." (PMID 35406689, 2022). "Circulating CD36 levels were positively correlated with severity of insulin resistance and atherosclerosis in several human population studies, and it was postulated that circulating CD36 could be used as a marker of metabolic syndromes." (PMID 35438721, 2022). "USP14 inhibitor IU1 significantly increases CD36 ubiquitination and stabilizes CD36 protein by removing the polyubiquitin chains, decreasing foam cell formation by downregulating CD36-mediated lipid uptake, and providing a potential therapeutic target for atherosclerosis." (PMID 35301297, 2022). "Therefore, it is plausible that DCHP increased atherosclerosis in PXRF/FLDLR−/− mice by stimulating CD36 expression and CD36-mediated lipid uptake and foam cell formation." (PMID 35406689, 2022). "Similar to APOB and CD36, the CALM1, CALM2, and CALM3 encoding calmodulin 1, 2, and 3, respectively were differentially expressed and downregulated on the lipid and atherosclerosis pathway." (PMID 36506940, 2022). "This study reveals a function of vimentin in CD36 trafficking and macrophage foam cell formation and may guide to establish a new strategy for the treatment of atherosclerosis." (PMID 35656400, 2022). "Therefore, DCHP-stimulated CD36 expression in macrophage likely contributes to increased foam cell formation and atherosclerosis development in PXRF/FLDLR−/− mice." (PMID 35406689, 2022). "Pharmacological modulation of platelet-LDL interaction via NOX-2, LOX-1 and CD-36 might potentially create new therapeutic opportunities to combat atherosclerosis." (PMID 33440673, 2021).
atherosclerosis (continued). "However, the heterodimer also directly regulates the expression of CD36 molecule, which plays a role in atherosclerosis development." (PMID 34440082, 2021). "Though previously CD36 has been implicated in metabolic dysregulation-associated pathological conditions, further studies are recommended to elucidate the role of CD36-mediated exosomal delivery of FFAs in the pathogenesis of obesity, diabetes, and atherosclerosis." (PMID 34869682, 2021). "For instance, it was reported that CD36 might promote foam cell formation in macrophages after ischemic injury, significantly contributing to inflammation and atherosclerosis progression." (PMID 33498620, 2021). "PCSK9 enhances platelet activation by binding to CD36, therefore contributing to atherosclerosis." (PMID 34071103, 2021). "Only studies have shown the effect of noncoding RNAs on FAT/CD36 in atherosclerosis." (PMID 34803512, 2021). "While CD36’s involvement in the pathogenesis of arteriosclerosis must be addressed in future research, its exosomal form can act as a marker for prediabetes and atherosclerosis." (PMID 33921168, 2021). "In addition, future studies using LEC-specific CD36 knockout mice are required to determine the role of LEC CD36 in the regulation of arterial LV density, reverse cholesterol transport and development of atherosclerosis." (PMID 33672291, 2021). "Hence, both PEVs and CD36 are potential targets to hamper the development and progression of atherosclerosis." (PMID 33440673, 2021). "While EC do not accumulate lipids to form foam cells, we considered that interaction between EC CD36 and oxPC CD36 may contribute to the initiation phase of atherosclerosis through inflammatory pathways." (PMID 34888367, 2021). "Overexpression of miR-210-3p by inhibiting the IGF-2/IGF-2R axis could inhibit the expression of CD36 and NF-κB, then led to a reduction in the inflammatory response of macrophages and lipid accumulation in atherosclerosis." (PMID 33768092, 2021). "CD36 is one of the main scavenger receptors, which could regulate foam cell formation of macrophages, the early characteristic features of atherosclerosis." (PMID 34356896, 2021). "On the other hand, the interaction of CD36 with oxLDL can also activate the immune response and then result in the secretion of cytokines, which lead to immune cell infiltrates and finally promote the progress of atherosclerosis." (PMID 34539804, 2021). "On the other hand, exosomes from activated platelets also inhibit uptake of ox-LDL in macrophages, thereby preventing the formation of foam cells by reducing the expression of type II scavenger receptor CD36 in macrophages, ultimately inhibiting thrombosis in atherosclerosis." (PMID 34513963, 2021). "The binding of ox-LDL to CD36 also induces the release of various chemokines, such as monocyte chemotactic protein-1 and the interleukin 1β precursor, leading to the progression of atherosclerosis." (PMID 34071103, 2021). "In addition, in atherosclerosis, signals transmitted by oxLDL and CD36 in platelets or macrophages regulate downstream signaling molecules such as MLCK, which affects the cytoskeleton." (PMID 32190703, 2020). "We first demonstrate that the role of macrophage CD147 in atherosclerosis might involve promotion of ox-LDL-induced CD36-dependent cholesterol uptake and foam cell formation." (PMID 33490072, 2020). "Current evidence indicates that RCAN1 reduction is beneficial to atherosclerosis, which may have therapeutic potential for slowing or delaying the progression of atherosclerosis by inhibiting CD36 and VEGF signaling." (PMID 33267791, 2020). "Early studies focused more on the role of CD36 in atherosclerosis." (PMID 33344451, 2020). "Besides, oxLDL upregulates the expression of its receptor CD36 in macrophages and triggers inflammatory signaling through CD36 generating atherosclerosis." (PMID 32635347, 2020).
atherosclerosis (continued). "However, our data confirmed only CD36 was dependent on ER stress induced by SiNPs, leading to lipid accumulation and foam cell formation, which ultimately contributing to atherosclerosis." (PMID 33008402, 2020). "In particular, oxidized low-density lipoprotein (oxLDL) regulates the expression of dipeptidyl dipeptidase IV (DPP4) in macrophages leading to the increase of CD36 + cells which are representative of the inflammatory processes of atherosclerosis in obese and insulin resistant patients." (PMID 33414766, 2020). "Previous reports demonstrated that CD36 plays a crucial role during atherosclerosis development but it remains unclear how CD36 governs plaque myeloid cell metabolism." (PMID 39649554, 2020). "The effect of CD36 on atherosclerosis has been clearly established." (PMID 32733941, 2020). "Notably, we propose that the mechanism by which WISP1 alleviates lipid deposition of atherosclerosis is by reduction of SR‐A and CD36 expression, which is crucial to lipid deposition." (PMID 32851768, 2020). "Besides for oxLDL uptake, CD36 can also affect atherosclerosis by combining with various ligands, specifically in regulating inflammation, endothelial dysfunction, macrophage migration, and hyperlipidemia etc.." (PMID 33008402, 2020). "The authors found that administration of C1q/tumour necrosis factor-related protein 13 (CTRP13) reduced CD36 expression in vitro and significantly reduced aortic atherosclerosis in vivo, thus defining a potential novel therapeutic in atherosclerosis by SR modulation." (PMID 33182772, 2020). "Immunohistochemistry staining for CD36 was performed to verify the severity of atherosclerosis." (PMID 32292523, 2020). "CD36 is involved in a variety of biological processes, including lipid metabolism, inflammation, atherosclerosis, and angiogenesis, depending on the nature of the ligand to which it is exposed, since there are multiple proteins that bind to CD36, including TSP-1." (PMID 32626782, 2020). "Recent evidence suggested that dietary quercetin may be effective in lowering the risk of atherosclerosis by upregulating PPARγ, LXR-α, and ABCA1 and downregulating CD36 in the liver of apoE-/- mice fed HFD." (PMID 33261070, 2020). "From the immunohistochemistry staining results, we quantified the severity of atherosclerosis by calculating the ratio of CD36(+) area to intima-media area (IMA) as the indicate of inflammation severity, and the ratio of plaque area to IMA as the indicate of anatomical severity." (PMID 32292523, 2020). "CD36-targeted nanovesicles thus have potential for reducing atherosclerosis." (PMID 33182772, 2020). "Current work on SR regulation of atherosclerosis focuses largely on five SR classes: SR-A; SR-B (CD36 (cluster of differentiation 36)); SR-E (lectin-like oxidized LDL receptor-1 (LOX-1)); SR-G (CXCL16); SR-J (receptor for advanced glycation end-products (RAGEs))." (PMID 33182772, 2020). "Our results are consistent with a role for CD36 in promoting atherosclerosis." (PMID 31682178, 2019). "For example, miR-133a attenuates lipid accumulation via the testicular orphan nuclear receptor 4 (TR4)-CD36 pathway in macrophages and may serve as a potential biomarker and potent therapeutic agent for atherosclerosis." (PMID 31379931, 2019). "Our identification of the genetic locus responsible for inter-individual variation in non-deficient CD36 expression opens new areas of investigation into the link between this locus and platelet function, serum lipid levels, and atherosclerosis." (PMID 31344026, 2019). "However, CD36 has been studied in detail in some cells (monocytes-macrophages) and diseases (obesity, atherosclerosis/cardiovascular diseases), whereas other areas (tumor metastasis) are less covered." (PMID 31379931, 2019).